THBD (thrombomodulin)
Diseases named in the same sentence as THBD in open-access papers (continued):
Sharing a sentence is not in itself a finding about the gene and the disease.
Sepsis (continued). "While it would be intuitive to assume higher soluble thrombomodulin levels might have protective effects, trials of recombinant soluble thrombomodulin in the case of sepsis have largely been negative." (PMID 39941363, 2025). "The use of anticoagulants for DIC is considerably different between the countries, the Japanese Clinical Practice Guidelines for Management of Sepsis and Septic Shock recommend the use of antithrombin or recombinant thrombomodulin, while they were not recommended in the rest of the world." (PMID 39302568, 2024). "Although there was increased mortality with increased thrombomodulin in patients with sepsis and shedding of thrombomodulin in the previous report, the current study did not confirm whether rhTM interacted with soluble shed thrombomodulin." (PMID 36353180, 2022). "We postulate that since sTM is primarily derived from lung endothelium, patients with respiratory failure may be more likely to show a benefit from recombinant thrombomodulin compared to a population with non-pulmonary sources of sepsis." (PMID 34344416, 2021). "In adult sepsis, novel therapeutic options such as interleukin-22, anti-high mobility group box 1 (HMGB1) monoclonal antibody, vascular endothelial growth factor receptor monoclonal antibodies, and recombinant human thrombomodulin (rhTM) are the focus of preclinical investigation." (PMID 31941991, 2020). "Following these studies, the efficacy and safety of rTM in the adult patients with sepsis and coagulation disorders have been examined in a multinational, randomized, placebo-controlled, double-blinded phase III trial named SCARLET (Sepsis Coagulopathy Asahi Recombinant LE Thrombomodulin)." (PMID 31416465, 2019). "As analysis of long-term serial scores was not performed, we could not evaluate dynamic changes in serum thrombomodulin level with the development of sepsis." (PMID 28771554, 2017). "As documented in large randomized controlled trials (RCTs), the administration of either antithrombin III or human recombinant thrombomodulin could improve short-term mortality among septic patients, but no trails specifically targeted patients with postoperative sepsis." (PMID 32903618, 2020). "The analysis included age, gender, SAPS II score, presence or absence of sepsis and each of the biomarkers that showed significant differences between groups in bivariate analyses: IL-8, ICAM-1, protein C, PAI-1 and thrombomodulin." (PMID 18358078, 2008). "Assessing coagulation factors to clinical markers of severity, we observed that in COVID-19 patients, vWF, XIII, VIII, and thrombomodulin levels correlated with lung function impairment (defined by SOFA respiratory score), whereas such correlation was not seen in the other sepsis cohorts." (PMID 36829233, 2023).
COVID-19 (74 papers, 2020 to 2026). A disease caused by infection with severe acute respiratory syndrome coronavirus 2. "Angiopoietin-2, a pro-inflammatory cytokine, and cleaved thrombomodulin is elevated in plasma in severe COVID-19 and has been linked to endothelial dysfunction and hypercoagulability." (PMID 41620635, 2026). "In conclusion, determination of soluble thrombomodulin along with D-dimer enhances thrombotic risk assessment in hospitalized COVID-19 patients." (PMID 40106444, 2025). "Analysis of endogenous thrombin potential (ETP) in the plasma of COVID-19 patients showed that severe complications are associated with the development of resistance to the blood coagulation system inhibitor thrombomodulin (TM)." (PMID 39457048, 2024). "Previous studies on classic markers of fibrinolysis, including PAI-1, tPA, TAFI, and thrombomodulin have suggested an association with COVID-19 severity." (PMID 37373613, 2023). "Although some endothelial markers, such as thrombomodulin, have been already linked to mortality in COVID-19 patients, the predictive value of the PBR as an estimate of glycocalyx thickness has not been reported yet." (PMID 33058027, 2021). "This study aimed to determine the prognostic values of endothelial damage biomarkers (Syndecan-1 and thrombomodulin) in COVID-19 patients in China, as well as their associations with inflammation, coagulopathy, and mortality." (PMID 34861818, 2021). "Upregulation of TF expression has been associated with thrombus formation in COVID-19 lungs, while post-mortem specimens have demonstrated upregulated TF expression in the lung of fatal COVID-19 cases with loss of thrombomodulin, implying a shift towards a prothrombotic state." (PMID 37175942, 2023). "The anticoagulant proteins involved in the pathogenesis of coagulation disorders in the course of COVID-19 include thrombomodulin (encoded by the THBD gene) and protein C (encoded by the PROC gene), which are responsible for inhibiting thrombin generation at various stages of its formation." (PMID 36551272, 2022). "The profound downregulation of EPCR and thrombomodulin suggest that loss of constitutive antithrombotic function may promote clotting in COVID-19." (PMID 34506304, 2021). "Moreover, the results indicate enhanced activation of the alternative complement pathway is most prevalent in patients with severe COVID-19 and is associated with markers of endothelial injury (i.e., angiopoietin-2) as well as hypercoagulability (i.e., thrombomodulin and von Willebrand factor)." (PMID 34446527, 2021). "THBD expression was significantly reduced bith peritubular capillaries and glomeruli in COVID-19 kidneys." (PMID 41620635, 2026). "CONCLUSIONS: This study identifies widespread renal microthrombi, tubular necrosis, and reduced THBD expression in COVID-19 patients with AKI, supporting a role for endothelial dysfunction and microvascular thrombosis in COVID-19-associated renal injury." (PMID 41620635, 2026). "We aimed to determine the predictive accuracy of elevated soluble thrombomodulin (sTM) and angiopoietin-2 (Ang2) for thrombotic events (TE) in hospitalized COVID-19 patients." (PMID 40106444, 2025). "Patients with severe COVID-19 are characterized by increased activity of the coagulation system and suppression of the fibrinolytic system and the protein C–protein S—thrombomodulin system in blood plasma." (PMID 39457048, 2024). "The biomarkers for endothelial dysfunction, such as VWF, factor VIII, and soluble thrombomodulin levels, were significantly elevated in convalescent COVID-19 patients compared with those for the controls." (PMID 39199353, 2024). "Markers associated with endothelial dysfunction, such as von Willebrand factor antigen, soluble P-selectin, and thrombomodulin, hold promise as indicators of endothelial injury and coagulation abnormalities in COVID-19." (PMID 39359765, 2024).
COVID-19 (continued). "Goshua and colleagues demonstrated that an elevation in the shedding of thrombomodulin from endothelial cells in patients with acute COVID-19 has been observed, which impairs the anticoagulant activity of protein C (PC)." (PMID 38094124, 2023). "Pulmonary ECs of COVID-19 patients show increased expression of pro-coagulant vWf and decreased expression of the anticoagulants thrombomodulin (TM) and endothelial protein C receptor (EPCR)." (PMID 37175942, 2023). "In the present cohort of COVID-19 patients, thrombomodulin, IL-6, FVIII, VWF:Ag, sEPCR, sC5b9, tPA, PAI-1 activity, C4, ICAM-1 and VCAM-1 plasma levels were higher than normal ranges, in line with previous studies that included patients with a severe disease." (PMID 36143072, 2022). "The change in transcription of PROC and the activator receptors PROCR, FR2, and THBD in patients with COVID-19 suggests impaired cytoprotection and progression to the hypercoagulable state." (PMID 36560757, 2022). "We found that PROC, S1PR1, and THBD were downregulated in the nasal epithelium of patients with COVID-19." (PMID 36560757, 2022). "Changes in serum syndecan-1, thrombomodulin, and angiogenic factor concentrations were analysed during the first 24 h and 10 days after COVID-19 hospitalisation in patients with high-flow nasal oxygen or mechanical ventilation." (PMID 35372407, 2022). "In alignment to D-dimer, the other coagulation markers and thrombomodulin, prothrombin time (PT) were also elevated in patients with more severe COVID-19, which indicates coagulopathy." (PMID 34829418, 2021). "Low survival provability in COVID-19 patients with elevated levels of soluble thrombomodulin, a marker of endothelial injury, suggest endothelial injury in severe COVID-19 cases." (PMID 34177896, 2021). "The elevation of angiopoietin-2, thrombomodulin, endothelin-1, and vWF-A2 in fatal COVID-19 cases provides evidence for the involvement of endothelial injury in COVID-19." (PMID 33692097, 2021). "Consistently, biomarkers of endothelial dysfunction, such as thrombomodulin, VWF, angiopoietin 2, and plasminogen activator inhibitor-1, are frequently elevated, and seem to be associated with disease severity in COVID-19 patients." (PMID 34769508, 2021). "From the viewpoint of three pathophysiologies of COVID-19 coagulopathy, a theoretical rationale exists in antithrombin and recombinant human thrombomodulin for COVID-19 coagulopathy." (PMID 34177896, 2021). "Increased circulating thrombomodulin levels in severe COVID-19 likely reflect its cleavage from the cell surface." (PMID 34506304, 2021). "mRNA levels for regulators of the kallikrein–kinin (C1-inhibitor), coagulation (thrombomodulin, endothelial protein C receptor), and fibrinolytic (urokinase and urokinase receptor) pathways were significantly reduced in COVID-19 patients." (PMID 33683204, 2021). "Our results demonstrate upregulation of vWF and loss of thrombomodulin and EPCR in lung tissue from COVID-19." (PMID 34506304, 2021). "In this study, we measured two endothelial damage biomarkers (Syndecan-1 and thrombomodulin) in sera obtained from COVID-19 patients who were admitted to an ICU in Wuhan, China." (PMID 34861818, 2021). "Elevated levels of complement-related markers such as von Willebrand factor, thrombomodulin, and angiopoietin-2 are frequently observed in patients with severe COVID-19, underscoring the link between complement activation, endothelial dysfunction, and thrombotic complications." (PMID 41458994, 2025). "Also, by single-cell RNA-sequencing analysis of monocytes it was shown that the THBD gene was differentially upregulated in severe COVID-19 patients compared to monocytes from mild COVID-19 patients." (PMID 39132505, 2024).
COVID-19 (continued). "Endothelial dysfunction in COVID-19 induces a prothrombotic endothelial state, characterized by increased expression of tissue factor, von Willebrand factor, and impaired thrombomodulin and antithrombin activity, promoting coagulation activation and thrombus formation." (PMID 39359765, 2024). "Numerous investigations have documented heightened procoagulant activity in COVID-19 patients, characterized by elevated plasma levels of soluble thrombomodulin, suggesting increased endothelial cell activation, fibrin production, and resistance to fibrinolysis." (PMID 38979027, 2024). "However, the thrombin-thrombomodulin-EPCR complex is dysfunctional under COVID-19, affecting the aPC synthesis." (PMID 38378550, 2024). "Various studies have reported heightened procoagulant activity in COVID-19 patients, characterized by elevated plasma levels of soluble thrombomodulin, indicative of enhanced endothelial cell activation, augmented fibrin formation, and increased resistance to fibrinolysis." (PMID 38979027, 2024). "Another mechanism by which ANGPT2 could contribute to the prothrombotic state observed in COVID-19 is by thrombomodulin-dependent inhibition of the protein C pathway, as recently postulated." (PMID 38803346, 2024). "The anti-inflammatory properties of LMWH may be beneficial in COVID-19 patients and should be integrated with other antithrombotic treatments such as antithrombin, and recombinant thrombomodulin to hinder the complex “immunothrombosis” process." (PMID 36712996, 2023). "However, those with DSS and severe COVID-19 had elevated levels of thrombomodulin, plasminogen activator inhibitor type 1 and von Willebrand factor antigen suggesting that like COVID-19, activation of procoagulant mechanisms also occur in severe dengue." (PMID 35786403, 2022). "Loss of the constitutive endothelial anticoagulants such as TFPI, EPCR, and thrombomodulin is an important component of the prothrombotic endothelial transformation and may be an underappreciated driver of COVID-19 coagulopathy." (PMID 34506304, 2021). "Patients with COVID-19 had elevated D-dimer, thrombomodulin, and initial factor V elevation followed by decreased factor V and factor VII and elevated IL-6, lactate dehydrogenase, and c-reactive protein, which indicated coagulopathy and possible cytokine storm." (PMID 34829418, 2021). "Increased levels of thrombomodulin (CD141), a cofactor for thrombin reducing blood coagulation, possibly possessing an anticoagulant potential, were observed on cMonos in both moderate and severe disease, and on iMonos and ncMonos in severe COVID-19." (PMID 33479167, 2021). "Recent studies reported the levels of Syndecan-1 and thrombomodulin in COVID-19 patients." (PMID 34861818, 2021). "They observed that endotheliopathy is present in COVID-19 and is associated with increased mortality, with a suggestion that soluble thrombomodulin concentrations may predict mortality and clinical outcomes in COVID-19 patients." (PMID 33195487, 2020). "The biomarkers for endothelial dysfunction, including VWF, factor VIII, and soluble thrombomodulin levels, were significantly elevated in convalescent COVID-19 patients compared with those for the controls, suggesting that endothelial dysfunction may contribute to long COVID-19 pathogenesis." (PMID 39199353, 2024). "Those compounds have been shown to participate in pulmonary diseases and exert various effects, including a decrease in thrombomodulin that may be related to disseminated vascular coagulation, proposed as one of the mechanisms involved in COVID-19, and D-dimer elevation." (PMID 35629227, 2022). "In addition, some studies have found that the expression of thrombomodulin and protein C receptor on endothelial cells in COVID-19 patients is significantly decreased, and its mechanism is related to the infiltration of immune cells in the lungs of COVID-19 patients." (PMID 36408343, 2022).
COVID-19 (continued). "However, severe inflammation in COVID-19 patients is believed to be correlated with endothelial dysfunction, as seen in higher levels of thrombomodulin and sVCAM-1 (soluble vascular cell adhesion molecule-1), which is the only independent biomarker associated with mortality." (PMID 36014561, 2022). "In addition, considering that THBD, PROCR, and F2R are also involved in the regulation of the inflammatory response, we suggest another important interface that supports the involvement of APC in the pathogenesis of the COVID-19-associated coagulopathy." (PMID 36560757, 2022). "Plasma from patients with severe or moderate COVID-19 induced significant upregulation of genes encoding tissue factor, E selectin, and Angpt-2 and concurrently decreased the expression of antithrombotic genes encoding endothelial protein C receptor (EPCR), TFPI, and thrombomodulin." (PMID 34506304, 2021). "HUVEC supernatants stimulated with serum from patients with severe COVID-19 exhibited elevated levels of sICAM-1, sVCAM-1, P-selectin, sE-selectin, PECAM-1, tissue factor, and thrombomodulin compared to those stimulated with control medium." (PMID 41583455, 2025). "In this sense, the thrombin-thrombomodulin-EPCR complex has been often observed dysfunctional under both DM and COVID-19, affecting aPC synthesis." (PMID 38378550, 2024). "The observed trend of increased mortality in conjunction with elevated levels of thrombomodulin and d-Dimer on day 5 may be attributable to disease progression, occurrence of micro-thrombosis in intervening period, increasing systemic inflammation due to COVID-19 or secondary infections." (PMID 38263377, 2024). "Our data add to the findings on various markers of endothelial cell and platelet activation, including vWf, soluble thrombomodulin, soluble CD40 ligand, and plasminogen activator inhibitor (PAI)-1, studied in COVID-19." (PMID 33477776, 2021). "Specifically, markers supporting a procoagulant endothelial phenotype including Angpt-2, P selectin, thrombomodulin, and TFPI were all elevated in severe disease compared with moderate COVID-19 in our cohort." (PMID 34506304, 2021). "Additionally, severe COVID-19 cases also displayed elevated levels of factor VIII and thrombomodulin." (PMID 36829233, 2023). "Moreover, circulating levels of P-selectin, E-selectin, soluble intercellular adhesion molecule-1 (ICAM-1), thrombomodulin, angiopoietin-2, and plasminogen activator inhibitor-1 (PAI-1) are augmented in COVID-19." (PMID 37108759, 2023). "TGT without thrombomodulin (TM) addition showed statistically significant differences in the thrombin peak heights between COVID-19-positive and negative patients." (PMID 36555872, 2022). "Likewise, the higher circulating levels of thrombomodulin in COVID-19-although non-significant after removal of immune deficient patients-may reflect augmented shedding from the endothelial cell surface, which is expected to result in a loss of its cell-associated anticoagulant properties." (PMID 35660785, 2022). "Similar levels of ICAM-1, thrombomodulin, and P-selectin levels were observed between COVID-19 positive and negative patient cohorts." (PMID 34491250, 2021). "However, biomarkers of endothelial damage, such as thrombomodulin, vWF, angiopoietin 2, and PAI1, are often elevated in COVID-19 patients, and have prognostic relevance." (PMID 34451848, 2021). "To further elucidate the involvement of the endothelium in COVID-19 and its relation to EASIX, we have applied an endothelial biomarker panel to COVID-19, including angiopoietin-2 (ANG2), soluble thrombomodulin (sTM), suppressor of tumorigenicity-2 protein (ST2), and correlated them with EASIX." (PMID 34248931, 2021). "Despite limited COVID-19 autopsy specimen availability, we observed increased levels of the prothrombotic endothelial protein vWF and decreased levels of antithrombotic endothelial proteins EPCR and thrombomodulin." (PMID 34506304, 2021).